IL10 (interleukin 10)
Diseases named in the same sentence as IL10 in open-access papers (continued):
Sharing a sentence is not in itself a finding about the gene and the disease.
Sepsis (continued). "A high IL-10/IL-17A ratio, observed in newborn sepsis, sustains tissue DEL-1 expression, as IL-10 upregulates while IL-17 downregulates DEL-1." (PMID 38263289, 2024). "Andrographolide was reported to increase the anti-inflammatory factor IL-10 levels in the peritoneal cavity fluid of mice with cecal ligation and puncture (CLP)-induced sepsis." (PMID 39227945, 2024). "Here the authors identify that the IL-10/DEL-1 axis is involved in emergency granulopoiesis in neonates and suggest a link to sepsis survival in early life." (PMID 38263289, 2024). "Anti-inflammatory IL-10 levels were significantly increased with UC-MSC treatment as compared to controls at 0-6, 7-24, 25-48, and 49-72 hours post sepsis induction." (PMID 38381583, 2024). "In contrast, during the late stage of sepsis, M2-like macrophages can be activated by Th2 cytokines (IL-4 and IL-13), TGF-β, IL-10, glucocorticoids, and immune complexes." (PMID 39252831, 2024). "The model for sepsis (CD86%, platelets, interleukin-10, and procalcitonin) and the model for death (HLA%, respiratory rate, and platelets) had an area under the curve (AUC) of 0.870 and 0.843, respectively." (PMID 38603712, 2024). "The AUC of the model composed of CD86%, PLT, IL-10, and PCT to predict the occurrence of sepsis was 0.870 (0.800 sensitivity and 0.857 specificity)." (PMID 38603712, 2024). "We further explain the mechanistic basis of the discrepancy in DEL-1 expression between neonates and adults in sepsis, by demonstrating that DEL-1 is under the control of IL-10 and particularly of the IL-10 to IL-17A ratio." (PMID 38263289, 2024). "This study seeks to emphasize the potential of biomarkers, including IL-10, CRP, and PCT, in enhancing the early diagnosis and prediction of sepsis severity in patients." (PMID 39507174, 2024). "In a sepsis mouse model, EVs produced by MSC by significant upregulation of IL-10 generation, inhibit the entry of cytokines into the systemic circulation and reduce the infiltration of neutrophils and monocytes, showing an anti-sepsis effect." (PMID 39698413, 2024). "In the early stage of sepsis, monocytes/macrophages are rapidly recruited and release many inflammatory cytokines (e.g. IL-1β, IFN-γ, IL-6, TNF-α, and IL-10); subsequently, chemokines are released and acted on involved organs." (PMID 39320524, 2024). "MDSCs not only suppress the number and function of T cells, but also enhance the number of Treg, and produce cytokines with immunosuppressive function, such as IL-10 and TGF-β, impacting the prognosis of patients with sepsis." (PMID 38609858, 2024). "Resistin had a distinct connection with the severity of the illness, as shown by APACHE II and SOFA scores, and showed a correlation with well-established indicators of cytokines, such as IL-6, IL-8, IL-10, TNF-α, and sepsis." (PMID 38562275, 2024). "As expected, IL-4, IL-6, IL-10, IL-17, TNF-α, and CCL2 were significantly elevated from the early stage of sepsis, but on CLP day 6, all cytokines were reduced to levels similar to those of sham mice." (PMID 38385073, 2024). "ELISA results revealed that, compared to the normal group, the protein levels of TNF-α, IL-6, IL-10, and MCP-1 were increased in the sepsis model (P < 0.05)." (PMID 38961068, 2024). "What’s more, Th2 cells, along with monocytes/macrophages, secreted IL-10, which inhibits the expression of TNF-α in monocytes, promote the proliferation of MDSCs and aggravate immunosuppression in advanced sepsis mice and patients." (PMID 39267971, 2024). "Our results showed that genes such as IFN-γ, TNF-α, IL-6, MIP-2, IL-10, KC (CXCL1), CCL-2, MPO, MMP9, TLR2, and LCN2 were significantly upregulated in the lungs of sepsis-induced ARDS mice compared to control mice." (PMID 37822934, 2023).
Sepsis (continued). "IL-10, commonly produced by monocytes/macrophages and TH2 cells, was demonstrated to be increased and related to the outcome of sepsis; moreover, IL-10 exhibited both pro- and anti-inflammatory effects on innate and adaptive immunity in the septic environment." (PMID 38029224, 2023). "The pathogenesis of sepsis is accompanied by the overactivation of various inflammatory factors, including IL‐1β, TNF‐α, and IL‐10." (PMID 37382273, 2023). "Further research was conducted to reveal the associations between m6A patterns and inflammatory factors, including interleukin (IL)-1β, IL-8, IL-10, IL-11 and TNF receptor superfamily member 1A (TNFRSF1A), in sepsis." (PMID 36781867, 2023). "Some exceptions exist; for example, it is known that peritoneal neutrophils produce high amounts of IL-10 in the early phase of cecal ligation and puncture–induced (CLP-induced) sepsis." (PMID 37261908, 2023). "In contrast, LPS increased the supernatant IL-1β, IL-6, IL-8, IL-10, and TNF-α concentrations at 24 and 48 h better in patients with trauma than sepsis." (PMID 36615909, 2023). "IL-10 is an anti-inflammatory cytokine while IL-1β, INF-γ, and COX-2 are expressed during pathological inflammatory conditions, such as sepsis." (PMID 36662218, 2023). "Our findings that Hotairm1 knockdown in late sepsis MDSCs from mice and humans increased S100A9 phosphorylation and reduced IL-10 production are biologically significant." (PMID 39665047, 2023). "In contrast, M2 polarization and the release of large amounts of IL-10, TGF-β, and various anti-inflammatory mediators during the later phase of sepsis induce immunosuppression and the development of secondary infections." (PMID 36774341, 2023). "Following sepsis by cecal ligation and puncture, AMs reduce their production of CXCL1 and phagocytic uptake of bacteria in a TNF-α/interleukin-10 (IL-10) mediated manner." (PMID 36829255, 2023). "Our data show that IL-10 and Foxp3 are elevated in CD4+ T cells in the periphery of sepsis survivor mice as depicted by the % of IL-10+ CD4+ T cells and Foxp3+ CD4+ T cells." (PMID 37175808, 2023). "Consensus cluster analysis we successfully classified sepsis patients into two distinct groups based on the expression of 8 hub genes (IGFBP7, GMFG, IL10, IL18, ETS2, HGF, CD55, and MMP9)." (PMID 38259686, 2023). "In this study, SJS can improve the 7-day survival rate of sepsis mice, inhibit the release of inflammatory cytokines IL-1β, IL-6, TNF-α, and increase the production of IL-10 in the early stage." (PMID 37062835, 2023). "The reduced human leucocyte antigen DR molecules expression on RM enables their co-culture with PBMCs of sepsis patients which resulted in reduced ROS production, and up-regulated TGF-β while down-regulating IL6, IL8, and IL-10 in-vitro." (PMID 37696985, 2023). "Inflammatory markers as IL-6, IL-10 and procalcitonin have a predictive value only in HCMV seropositive patients in sepsis." (PMID 37907989, 2023). "Using specific ELISA parameters, we analyzed the levels of porcine CRP, haptoglobin, IL-4, IL-10, PGE2, TGF-ß and porcine alpha-1 acid glycoprotein, as we considered these to be fundamental sepsis biomarkers according to existing clinical research." (PMID 38087374, 2023). "In contrast, M2-type macrophages produce high levels of Arg-1, CD206, IL-10, and transforming growth factor beta (TGF-β), which play an immunomodulatory role and have a therapeutic effect on sepsis." (PMID 38066526, 2023). "IL-10 (interleukin-10), IL-4 (interleukin-4), and TGF-β (tumor growth factor beta) are the three best described anti-inflammatory regulators operating in sepsis." (PMID 37627293, 2023). "CLP—sepsis induced an acute increase in both inflammatory (IL-6 and MCP1) and anti-inflammatory (IL-10) serum cytokine concentrations." (PMID 37696985, 2023). "As well-known anti-inflammatory cytokines, IL-10 and transforming growth factor beta (TGF-β) act to modulate the inflammatory response during sepsis." (PMID 38029224, 2023).
Sepsis (continued). "In line with this, treatment with the immunoregulatory molecule ethyl pyruvate reduced lung levels of IL-10 and the expression of FOXP3 in lung-derived Tregs in a two-hit model of sepsis, reversing P. aeruginosa secondary pneumonia." (PMID 37426029, 2023). "CLP-induced experimental sepsis resulted in a significant upregulation in the expression levels of TNF-α, IL-1β, IL-6, IL-10, ROS and MDA." (PMID 36608000, 2023). "We found an increase in the expression of IL-6, IL-8, IL-10, IL-18, IL-33, IP-10, MIF, MIP1a, MIP1β, MIP3a, LEPTIN, GCSF, MCSF, and ESelectin in sepsis plasma compared to w/o sepsis and HC." (PMID 35681439, 2022). "IL-2R, IL-6, IL-8, IL-10, CCL-2, ICAM-1, and Urokinase were significantly higher in sepsis patients than SIRS patients." (PMID 35363162, 2022). "These pathways show shared entities and provide a clear link with IL-10 signalling, IL-1 signalling, and HSP60 and HSP70/TLR signalling pathways, known to be involved in sepsis." (PMID 35264246, 2022). "In our study, an early release of TNF-α at 6 h was noted, while the time-dependent kinetics of other detected biomarkers (IL-10, bET and HMGB1) were consistent with sepsis progression." (PMID 35615093, 2022). "The cytokine levels of IL-2R, IL-6, IL-8, IL-10, and MCP-1 were significantly increased in sepsis patients compared with SIRS patients." (PMID 35363162, 2022). "Sepsis induced an overexpression of the inflammatory mediators TNF-α, (p < 0.001) IL-6, (p < 0.001), IL-1β (p < 0.001) and IL-10 (p < 0.01)." (PMID 35795581, 2022). "Diversely, in mice with sepsis induced by intraperitoneal injection of LPS, the decreased CD5+CD1dhi Bregs and IL-10-producing B cells in severe endotoxic shock mice were observed compared with controls." (PMID 36425582, 2022). "Patients in the sepsis group had higher PCT, WBC, CRP, IL-1β, IL-2, IL-6, IL-8, IL-10, IL-12, IL-17, IFN-γ, and SOFA scores than those in the infection group, and the difference was statistically significant (P < 0.05)." (PMID 35937269, 2022). "We noted 11 common DNA binding sites in periodontitis and IL-10-stimulated neutrophils, 625 in NMOSD and TNF-α-stimulated neutrophils, and 19 in sepsis and LPS-stimulated neutrophils." (PMID 35757755, 2022). "Among the ICU Day-1 classifying proteins IL-10, CCL23, and TGFα1, significantly decreased in sepsis patient plasma by Day-3." (PMID 36572854, 2022). "Mice treated with LR17 had decreased sepsis severity demonstrated by lower levels of IL-6, TNF-a, and IL-10 in serum, peritoneal and bronchoalveolar fluid, and IL-6 and TNF-a in the liver, and lung." (PMID 35784361, 2022). "IL-10 levels ≤125.3 ng/L, APACHE score >30, and PMR >70.33 were significantly associated with the mortality rates of all patients, indicating that these three parameters determined before the hemadsorption may be good predictors of mortality among ICU patients with sepsis." (PMID 35317038, 2022). "These associations between pre-sepsis immune dysfunction and mortality are supported by studies showing that sepsis impairs production of IL-1, IL-6, TNF-α, IL-12, and IFN-γ and suggesting that this sepsis-induced immunosuppressive state may be augmented by release of IL-4 and IL-10." (PMID 35271683, 2022). "In our study, IL-10 was similar between wild-type and GPR174-deficient Tregs after hindlimb ischemia, the difference might possibly be related to the degree of inflammation response, in that inflammation response is overwhelming in sepsis model, while ischemia is dominant in our HLI model." (PMID 36473866, 2022). "IL-10 and IFN-ɣ have important regulatory roles in the host immune response and are involved in sepsis-induced immunosuppression." (PMID 35938048, 2022). "Wild–type mice exhibited rapid induction of TNF–α and IL–6 in the early stage of sepsis and a significant decrease in TNF–α and IL–6 levels thereafter and increased production of antiinflammatory IL–10 cytokine in the LPS model." (PMID 35911737, 2022).
Sepsis (continued). "We found in sepsis that the A2aR antagonist ZM241385 inhibited Treg expansion, CTLA-4 and Foxp3 expression, secretion of IL-10 and TGF-β and inhibitory activity on T-cell proliferation." (PMID 36148230, 2022). "We found that IL-6, IL-10 and TNF-α levels of the ZM241385-treated sepsis group were decreased in the blood and peritoneal cavity." (PMID 36148230, 2022). "Rs12196996 GG and rs2232365 AA were also correlated with increased level of miR-23a, IL-10 and decreased level of TNF, IL-2, IFN, IL-6 and IL-1β in the peripheral blood cell samples of patients with ICU-acquired sepsis." (PMID 35156517, 2022). "Anti-inflammatory cytokines such as IL-10 and TGF- are important inflammatory mediators in sepsis because they help prevent an overly proinflammatory response." (PMID 35449688, 2022). "B lymphocytes in sepsis display an exhausted phenotype, with reduced major histocompatibility complex class 2 (MHC II) expression and increased IL-10 production, an anti-inflammatory cytokine." (PMID 36470832, 2022). "Although several biomarkers are routinely used in clinical practice, including mHLA-DR, circulating IL-10, and CD4+/CD8+ ratio, the validity of many others is solely manifested in the pre-clinical studies using an experimental model of sepsis." (PMID 35619710, 2022). "Beyond procalcitonin, other frequently studied biomarkers such as CRP, IL-6, IL-8, IL-10, and TNF-α have had much less success predicting infection and sepsis." (PMID 39604183, 2022). "LPS-mediated sepsis significantly increased inflammatory cytokines than the control group, including TNF-α, IL-6, IL-10, MCP1, as well as ROS production, in the mouse heart." (PMID 35402535, 2022). "In vitro studies have shown that the anti-inflammatory cytokine interleukin 10 (IL-10) is a regulatory factor that blocks TNF-α, IL-1β, and IL-8 and many studies have found higher concentrations of IL-10 in patients with sepsis." (PMID 33997001, 2021). "The current study shows for the first time that both salivary IL-10 and CRP/MPV ratio showed statistically significant differences between neonates with late-onset sepsis and controls." (PMID 34676267, 2021). "The current study shows for the first time that both salivary IL-10 and CRP/MPV showed statistically significant differences between neonates with late-onset sepsis and controls." (PMID 34676267, 2021). "The anti-inflammatory effects of MSCs on host tissues by their secretion of TGF-β, IL-10, IL-4, and prostaglandin E2 have been reported in preclinical models of ARDS and sepsis." (PMID 33514427, 2021). "Its derivative, protocatechuic acid isopropyl ester, had been proved to protect murine model against sepsis by inhibiting TNF-α production, NO production, and the augmentation of IL-6 and IL-10." (PMID 34938184, 2021). "Whole blood from patients with simple sepsis showed a higher expression of TREM-1 and higher levels of IL-6, IL-8, IL-10 and TNF-α upon stimulation with LPS when compared with whole blood from patients with severe sepsis." (PMID 33924130, 2021). "We previously found that SPIONs significantly improved the symptoms of sepsis and liver injury, which was manifested by decreased levels of AST and ALT, decreased TNF-a and IL-6 levels, and increased IL-10 expression." (PMID 34627385, 2021). "We provide an overview of the current literature on the effects of IL-10, TGF-β and TSLP in sepsis and trauma and suggest therapeutic approaches for their modulation." (PMID 33717127, 2021). "We then identified inflammation in the mice with sepsis myocardial injury, and the levels of TNF-α, IL-6, IL-8, and IL-10 were evaluated using ELISA." (PMID 33819192, 2021). "LPS is a known stimulator in the systemic inflammatory mechanism of sepsis, LPS-triggered ROS generation, and the release of inflammatory cytokines, such as IL-1β, TNF-α, IL-6, and IL-10." (PMID 33986684, 2021).
Sepsis (continued). "Biomarkers associated with the innate immune system, especially soluble biomarkers such as cytokines IL-6 and IL-10, CRP, and procalcitonin have shown variable ability to identify hyper inflammation and/or sepsis." (PMID 34065206, 2021). "The results showed that at 6 h after sepsis, except for IL-6, TNF-α, IL-1β, and IL-10 levels decreased in DEX-treated mice." (PMID 33981237, 2021). "We showed better reductions in the AST, ALT, serum creatine, and cytokine levels (IL-6, IL-10, TNF-α, IFN-γ, MIP-2, and MCP-1) in both the early and late stages of sepsis." (PMID 34759282, 2021). "On the other hand, the levels of regulatory cytokines IL-10 and TGF-β were significantly increased in sera of sepsis mice receiving rSj-Cys-treated BMDMs compared with control mice receiving untreated or LPS-treated BMDMs or PBS only." (PMID 33718268, 2021). "The expression level of MALAT1 was significantly increased in sepsis in vitro, and MALAT1 knockout also reduced serum levels of cTn-I, TNF-α, IL-1β, IL-6, IL-10, IL-17, IFN-γ, C5, and C5a." (PMID 34514170, 2021). "It was found that sepsis-induced myocardial injury significantly promoted the release of TNF-α, IL-6, and IL-8 and decreased the IL-10 level, compared with that in the sham group." (PMID 33819192, 2021). "It has been reported that serum cytokines such as IL-1β, IL-6, IL-8, IL-10, IL-12, IL-17A, IL-18, interferon gamma (IFN-γ), and TNF-α are elevated in sepsis, but some of these cytokines are also elevated in FMF patients." (PMID 34654467, 2021). "High chloride fluids have also been shown in experimental sepsis models to increase TNF, IL-10, and IL-6 concentrations and to impair microcirculatory function compared to balanced crystalloids." (PMID 33718468, 2021). "In the sepsis patients, the serum levels of the proinflammatory cytokines IL-6, IL-8, MCP-1, and IL-10 were strikingly higher than those in healthy controls, and the serum levels of IL-1β were slightly elevated." (PMID 32826331, 2020). "Mice with sepsis showed an obvious intestinal barrier dysfunction with decreasing specific somatostatin receptor subtype (SSTRs), and increasing TNF-α, IL-6, and IL-10 in the ileum." (PMID 33376482, 2020). "Another 5–10-month follow-up study in sepsis patients showed an increased frequency of circulating FOXP3+ T cells, along with higher concentrations of IL-33 and IL-10 in their serum when compared to healthy controls." (PMID 33336293, 2020). "Nevertheless, during a septic process, anti-inflammatory cytokines (i.e., IL-10, IL-30, transforming growth factor-β (TGF-β), etc.)are also produced and continuously released, strongly influencing the sepsis progression and outcome." (PMID 32630422, 2020). "The reduced TNF-α and IL-6 levels were correlated with the increased IL-10 and TGF-β levels in sera of CLP-induced sepsis mice treated with rSj-Cys compared with the CLP group without treatment." (PMID 32423469, 2020). "The results suggested that CLP-induced sepsis mice stimulated the secretion of pro-inflammatory cytokines (TNF-α and IL-6), but inhibited the regulatory immune pathway (lower levels of IL-10 and TGF-β)." (PMID 32423469, 2020). "In conclusion, our results found that mice with sepsis showed an obvious intestinal barrier dysfunction with an increase of TNF-α, IL-6, and IL-10 in the ileum." (PMID 33376482, 2020). "The researchers also observed that the levels of IL-1β, IL-6, IL-10, MCP-1, and TNF-α were significantly increased in septic shock as compared with severe sepsis." (PMID 32153410, 2020). "• How do cytokines (IL-1RA, IL-4, IL-10, and TGF-β) with known anti-inflammatory effects contribute to the resolution of sepsis?" (PMID 32676795, 2020). "Likewise, targeting MDSCs/IL-10 directly or indirectly in other pathological conditions such as sepsis/infection, certain autoimmune disorders, and certain allergic disorders such as asthma could also provide a promising approach to control such pathological conditions." (PMID 32931721, 2020).